EPO (erythropoietin)
Diseases named in the same sentence as EPO in open-access papers (continued):
Sharing a sentence is not in itself a finding about the gene and the disease.
anemia (continued). "Subsequently, expert consensus panels of the American Association of Kidney Patients and of the National Kidney Foundation have recommended intravenous L-Carnitine for treatment of erythropoietin-resistant anemia, dialysis hypotension, cardiomiophaty and muscle weakness." (PMID 26612997, 2015). "Possible causes of low Hb level or anemia due to SHPT may be because of increased bone marrow fibrosis, which may lead to decreased erythropoietin and increased resistance to EPO." (PMID 26000281, 2015). "Indeed, in spite of the normal endogenous EPO levels that were similar to those of the control group, the 200 IU rHuEPO group developed anemia, suggesting that the anti-rHuEPO antibodies also neutralized the action of endogenous EPO." (PMID 25580431, 2014). "Anemia usually triggers erythropoiesis by increasing EPO production through the hypoxia-inducible factor (HIF) pathway, by mobilizing iron from the iron storage pool and by increasing iron absorption, in order to face the increased iron needs for erythropoiesis." (PMID 25580431, 2014). "Treatments for anemia include iron supplementation and erythropoietin stimulating agents." (PMID 24392162, 2014). "Apparently, erythropoietin response declines during development at a similar degree of anaemia." (PMID 25138388, 2014). "The therapeuticbenefits of erythropoietin beyond the correctionof anemia are still questioned." (PMID 24381864, 2014). "In addition, pentoxifylline can improve hemoglobin levels in renal failure patients with erythropoietin-resistant anemia." (PMID 24729879, 2014). "Interestingly, OSM KO mice showed some characteristics similar to the diagnostics of AA; i.e., fatty marrow, high serum EPO concentration, a high frequency in aged individuals, and anemia." (PMID 25551451, 2014). "We have not included HbA1c in diagnostic endpoints for NODAT, as it could be affected in early transplant period by anemia, uremia and erythropoietin usage." (PMID 24959347, 2014). "Bleeding also may reduce oxygen delivery to the myocardium and anaemia-induced erythropoietin release may promote a systemic prothrombotic state." (PMID 24820096, 2014). "EPO−/− and EpoR−/− mice die of severe anemia around embryonic day 13.5." (PMID 24918289, 2014). "With the corresponding decreased levels of erythropoietin in older children with the same degree of severe malarial anaemia, conceivably, the bone marrows of the younger children with acute malaria may be less sensitive to erythropoietin." (PMID 25138388, 2014). "Side effects included pruritus and anaemia leading to erythropoietin therapy." (PMID 25047566, 2014). "In a study by Corazza, cisplatin nephrotoxicity played no significant role in decreasing erythropoietin production, while it could reduce bone marrow response to erythropoietin due to cispaltin-induced anemia." (PMID 25598955, 2014). "However, although patients with CKD and anemia present with low serum EPO levels, their kidneys are still able to produce EPO in response to a hypoxic stimulus." (PMID 25392999, 2014). "Therefore, it is highly desirable to develop alternative therapies to rhEPO that have equivalent efficacy in the treatment of anemia while avoiding excessive plasma EPO levels." (PMID 25392999, 2014). "It is thus plausible to suggest that the high levels of erythropoietin in younger children with anaemia as compared to older children with relatively the same degree of anaemia may, presumably, protect them against tissue damage." (PMID 25138388, 2014). "Anemia may ensue destruction of peritubular fibroblasts and decrease in erythropoietin level even before detectable reduction in GFR." (PMID 25695026, 2014). "The use of erythropoietin-stimulating agents has been shown to be effective for anemia caused by peg- interferon and ribavirin without compromising SVR rates." (PMID 25948447, 2014).
anemia (continued). "The CHOIR trial also revealed increased risk or significantly greater hazard in patients with the higher hemoglobin target that was not seen in patients with diabetes or heart failure, indicating that comorbidities differentially affect outcomes in EPO treatment of anemia." (PMID 24918289, 2014). "Compared with controls, higher oxygen tension in failing kidneys has been directly demonstrated in the rat remnant kidney (subtotal nephrectomy) model, which is commonly used as a model for CKD that comprises proteinuria, uremia, reduced EPO production with anemia, and increased blood pressure." (PMID 25392999, 2014). "Treatment of anemia in CKD requires in many instances erythropoietin (EPO)." (PMID 24373521, 2013). "Similarly, administration of ACE inhibitors reduces plasma erythropoietin levels, exacerbating anemia." (PMID 24167502, 2013). "The recombinant human erythropoietin (rhEPO) is used in the treatment of anemia." (PMID 29805869, 2013). "A further uremic toxins that could contribute to anemia in chronic kidney disease is indoxyl sulfate, which is at least partially effective by suppression of erythropoietin production." (PMID 24188099, 2013). "This is the first ever report in estimating endogenous anti-EPO antibodies in malaria anaemia." (PMID 23978045, 2013). "We also evaluated whether enhancing erythropoiesis using EPO treatments may ameliorate LT-induced anemia, and thus, reduce the mortality of LT-treated mice." (PMID 23977125, 2013). "Anemia of HD can be managed relatively successfully by recombinant human erythropoietin." (PMID 25340139, 2013). "Bisialylated hEPO is an abundant glycoform of anemia-patients derived serum EPO." (PMID 23325672, 2013). "Meanwhile, EPO has been used successfully in a couple of diseases, treating anaemia in AIDS, in renal failure, as well as for limiting brain damage in experimental auto-immune encephalomyelitis, and also been proposed for treatment of haemoglobinopathies in which β-globin synthesis is affected." (PMID 23978045, 2013). "Overall, we expect EPO treatment in thermally injured patients to be safe and beneficial when combined with an adequate anti-thrombotic prophylaxis, as has already been seen for decades in patients with anemia due to renal failure." (PMID 23782555, 2013). "Thus, the level of anti-EPO antibodies in malaria anaemia situation of different strains of semi-immune mice was evaluated." (PMID 23978045, 2013). "Third, the data which allow the classification of the causes of anemia such as reticulocyte counts, erythropoietin levels, iron turnover, and parvovirus IgM titers were not measured." (PMID 24058490, 2013). "This limits the use of recombinant human EPO (rhEPO) to treat anaemia in cancer patients, because the rhEPO may be stimulatory to the cancer." (PMID 23305401, 2013). "The reason of anemia in cirrhosis may be multifactorial, including decreased erythrocyte survival, reduced erythropoietin levels or hypersplenism." (PMID 23776499, 2013). "It was concluded that reversal of anemia by EPO retards the progression of renal failure, especially in non-diabetic patients (they speculated that this was due to prevention of renal tissue hypoxia)." (PMID 25340147, 2013). "Anaemia was infrequent due to the use of erythropoietin and only occurred in 13 patients (13%)." (PMID 23599749, 2013). "Interestingly, the progression of anaemia is at relatively low parasitaemia with some mortality in the semi-immune individuals in the endemic areas despite adequate erythropoietin (EPO) synthesis." (PMID 23978045, 2013). "Anemia in end-stage kidney disease can be managed by recombinant human erythropoietin (EPO)." (PMID 25340139, 2013). "Anaemia is routinely treated by erythrocyte transfusions or erythropoietin (EPO) administration." (PMID 23755260, 2013).
anemia (continued). "This included observational studies of the use of recombinant erythropoietin to correct anemia and studies of phosphorus binders to ameliorate hyperphosphatemia in patients with CKD that showed beneficial effects on mortality, CVD outcome, and progression of renal disease." (PMID 24066946, 2013). "On the other hand, hepcidin is downregulated by anemia, hypoxia, and erythropoietin." (PMID 23433094, 2013). "That patient’s treatment course was complicated by severe anemia (the lowest hemoglobin level was 6.9 g/dL), which led to use erythropoietin, and a reduction of RBV from 800 mg/day to 600 mg/day in the first half of treatment and a further decrease to 400 mg/day in the latter half of treatment." (PMID 24348635, 2013). "EPO expression is tightly regulated by developmental, physiological, and cell-type-specific factors during development, which can be activated in response to acute anemia or hypoxia to functionally regulate erythropoiesis." (PMID 23936170, 2013). "This outcome is due to the loss of renal mass in patients with CRF, associated with endocrine disorders such as a deficiency of erythropoietin (95% of which is produced in the kidney, and which is necessary for RBC maturation), which leads to the development of anaemia." (PMID 24396309, 2013). "Iron administration plays a central role in enhancing anemia responsiveness to EPO." (PMID 25340139, 2013). "Therefore, EPO therapy has become the standard treatment for the anemia of CKD (chronic kidney disease)." (PMID 24282790, 2013). "However, randomized controlled trials (RCTs) on the use of EPO for purposes other than the treatment of hypo-regenerative anemias remain scarce." (PMID 22094132, 2012). "The risk of infection could therefore be further reduced by more effective management of anaemia with iron supplementation and erythropoietin." (PMID 23082935, 2012). "Unexplained anemia was characterized by unexpectedly low EPO and low lymphocyte count." (PMID 23091709, 2012). "Decreased erythropoietin production and/or impaired bone marrow response to erythropoietin may also play an important role in the development of anemia." (PMID 24066259, 2012). "EPO production is hypoxia inducible and thus increases during anemia and hypoxic stress." (PMID 22567318, 2012). "It is of potential clinical interest to suggest that BAFF may comprise a rationale anti-anemia agent for possible use in combination with EPO." (PMID 22808010, 2012). "In developing countries where patients cannot afford EPO, anaemia is treated mainly with recurrent blood transfusions with attendant risks of complications such as transfusion transmissible infections, especially in the current pandemic of human immune deficiency virus infection." (PMID 23119160, 2012). "Hemolysis results in high concentrations of free heme and oxidative stress, which may contribute to altered bone physiology in hemoglobinopathies and may further enhance anemia and concomitant production of EPO by inducing erythropoietic distress." (PMID 23029401, 2012). "Anemia is common due to a number of factors including impaired erythropoietin production." (PMID 22829845, 2012). "However, the amount of EPO produced under these conditions has been considered to be inadequate relative to the degree of anemia." (PMID 22094132, 2012). "Anemia of CKD results from underproduction of endogenous erythropoietin by the kidneys." (PMID 22577528, 2012). "The efficacy of EPO on the anaemia of patients with GIST treated with imatinib was analyzed." (PMID 22950685, 2012). "Hence, the dose of EPO required to attain a tissue protective effect in heart and brain ischaemia is much higher than that used for the management of anaemia in renal failure." (PMID 22462027, 2012).
anemia (continued). "Peginesatide (formerly known as HematideTM) is a synthetic, PEGylated, investigational, peptide-based ESA that has an amino acid sequence unrelated to endogenous EPO and is currently being developed in the United States for the treatment of anemia due to CKD in patients on dialysis." (PMID 22188389, 2012). "Subsequently, it has been a controversial issue whether rhEpo and its analog erythropoietin stimulating agents are detrimental for the treatment of anemia in cancer patients by promoting cancer cell survival and angiogenesis." (PMID 23028796, 2012). "EPO, a hormone necessary for production of red blood cells, function primarily to transport oxygen, is synthesised by the adult kidney cortex, and the production can be induced by anaemia or hypoxic stress." (PMID 22844537, 2012). "EPO is used widely for treating anemia of critical illness or anemia induced by chemotherapy." (PMID 21943500, 2011). "Anaemia in all the dogs may be due to chronic renal disease which results from decreased production of erythropoietin and depressed erythrogenesis and/or shortened erythrocyte life span due to accumulation of uraemic toxins." (PMID 23738110, 2011). "A possible explanation is that the strong influence of anemia in our sample may be hiding the contribution of other factors, besides Hb, to the expression of EPO." (PMID 21912616, 2011). "Additionally, we confirmed that the increase in Hb levels and its duration by EPO-hyFc(H) after the induction of more severe anemia were comparable to that in mild anemic rats." (PMID 21957455, 2011). "The aims of our study were to determine (a) the EPO and ferritin levels in de novo and treated lymphoma patients, and (b) whether there is a relationship between EPO level and ferritin response to anemia." (PMID 21713081, 2011). "Although some aspects of this anaemia can be corrected, by administration of erythropoietin, iron supplementation and other measures, its presence itself indicates the severity of the underlying disease process and is highlighted through the presenting clinical condition of the patient." (PMID 22548027, 2011). "Anemia can be treated by administration of erythropoiesis-stimulating agents, that is, EPO." (PMID 22203913, 2011). "Also an age-dependent EPO response to anemia has been described in malaria-endemic areas, coinciding with the distribution of SMA in younger ages and CM in older ages." (PMID 21912616, 2011). "This is most likely due to EPO response to anemia in lymphoma patients." (PMID 21713081, 2011). "Patients with reduced or absent endogenous erythropoietin production may need to receive exogenous erythropoietin as replacement therapy for the stimulation of erythropoiesis and correction of their symptomatic anaemia." (PMID 21331363, 2010). "When renal function is reduced, erythropoietin production is impaired, which could limit erythropoietin-induced neuronal protection against anemia-induced stroke." (PMID 20950484, 2010). "The crucial importance of the EPO-EPOR-JAK2-STAT5 axis has been demonstrated by knock out studies in mice that showed how lack of each one of these four molecules results in a lethal phenotype (death due to severe anemia) during fetal development." (PMID 20508726, 2010). "Further, whereas mice treated with human erythropoietin showed a transient increase in hematocrit, those that received human erythropoietin containing low levels of IIRMIs had reduced response to erythropoietin after the 1st dose and developed long-lasting anemia following subsequent doses." (PMID 21203556, 2010). "Cancer patients may develop anaemia as a result of disease characteristics, chemotherapy or due to decreased endogenous erythropoietin production." (PMID 21331363, 2010).
anemia (continued). "A few reports investigated only erythrocyte complement receptor type 1 (E-CR1) among HD patients as follows: recombinant human erythropoietin improved anemia and increased the level of E-CR1, and a low level of E-CR1 was associated with poor prognosis in HD patients." (PMID 21134272, 2010). "A blunted production of EPO complicates the pathophysiology of anaemia." (PMID 21415945, 2010). "The profound anemia that results from production of only a few hypochromic and microcytic red blood cells leads to a dramatic increase in erythropoietin (EPO) levels, that ultimately drive an uncontrolled expansion of additional early erythroid progenitors inducing massive EMH." (PMID 20508726, 2010). "Investigation for evidence of overt bleeding or hemolysis was negative, suggesting that anemia was due to diminished EPO levels associated with ARF." (PMID 19166584, 2009). "It has been suggested that the use of erythropoietin may be an appropriate strategy for managing anaemia, improving quality of life and increasing adherence to therapy, especially in patients with genotype 1 infection." (PMID 18761607, 2009). "Unfortunately, in the clinical setting, most cases of acute kidney injury are not identified until some time after renal functional deterioration has occurred and significant anemia emerges several days later, decreasing the likelihood that EPO would be administered early in the course of ARF." (PMID 19166584, 2009). "Similarly, Cooper and associates administered oxpentifylline (400 mg daily per os) for 4 months to 16 ESKD patients with EPO-resistant anaemia (defined as a haemoglobin level < 107 g/L for 6 months before treatment and an EPO dose ≥ 12,000 IU/week)." (PMID 18671885, 2008). "The main hypothesis of this study is that Oxpentifylline administration will effectively treat erythropoietin- or darbepoietin-resistant anaemia in chronic kidney disease patients." (PMID 18671885, 2008). "These inflammatory cytokines can also interfere with endogenous erythropoietin (eEPO) production which may contribute further to the anaemia observed in MDS patients." (PMID 18540943, 2008). "Blood levels of erythropoietin are upregulated in response to anemia or arterial hypoxemia." (PMID 18380894, 2008). "In addition to EPO therapy, 97% of the patients received at baseline anti-anaemia adjuvant medication." (PMID 19077225, 2008). "The systemic administration of putative anti-angiogenic agents targeting erythropoietin and its receptor may be limited by the development of anemia due to the suppression of erythropoiesis." (PMID 17579721, 2007). "In addition, the beneficial effects of erythropoietin on anaemia, functional status and quality of life of cancer patients receiving chemotherapy have been demonstrated by several large randomised and nonrandomised studies." (PMID 16909132, 2006). "The apparent transient impact of HIV on the EPO response to anemia might suggest that the attenuating effect on EPO is more pronounced closer to the time of initial infection and weakens with progression of HIV disease." (PMID 16390553, 2006). "While it is likely that CKD, advanced age or certain medication exposure may play a role in the development of anemia in this population, at least one study points to the possible role of inflammation and resistance to elevated levels of erythropoietin." (PMID 17042950, 2006). "The etiology of anemia of critical illness remains unclear, but a blunted endogenous EPO response appears to play a role." (PMID 15987387, 2005). "• The EPO response to anemia in the critically ill mechanically ventilated patient is blunted." (PMID 15987387, 2005). "Rogiers and coworkers compared a mixed population of critically ill patients with iron deficient control patients to determine whether a relationship between EPO response and degree of anemia existed." (PMID 15987387, 2005).